TOP2A (DNA topoisomerase II alpha)
Diseases named in the same sentence as TOP2A in open-access papers (continued):
Sharing a sentence is not in itself a finding about the gene and the disease.
glioma (continued). "Univariate COX regression showed that TOP2A, AGE, GRADE, IDH mutation, and 1p19p deletion are considered clinically relevant to glioma." (PMID 41284119, 2025). "This study does not directly prove the mechanism of the occurrence and development of TOP2A and glioma, but to a certain extent, it reveals their interconnection, and the specific mechanism needs to be further revealed in future studies." (PMID 41284119, 2025). "Through the expression distribution, we can find that the expression degree of TOP2A in glioma is different, and there is a certain trend change." (PMID 41284119, 2025). "Gliomasphere line specific (EGFR) and cell cycle markers (MKI67, TOP2A) dominated clustering and we noted enrichment of glioma stem cell (PTPRZ1, SOX2) and astrocytic markers (GFAP, S100B) in GS025." (PMID 38856710, 2024). "ORC6 emerged as a crucial regulator for the expression of key oncogenic genes, including Cyclin A2, Cyclin B2, and DNA topoisomerase II (TOP2A), within glioma cells." (PMID 38971772, 2024). "Conversely, overexpression of ORC6 in primary human glioma cells led to an increase in TOP2A expression." (PMID 38971772, 2024). "TOP2A stimulates glioma cell metastasis possibly by initiating the transcriptional activation of β-catenin." (PMID 38971772, 2024). "Alterations or increased expression of TOP2A in glioma cells can lead to heightened genomic instability and uncontrolled cell proliferation, often correlating with more aggressive tumor behavior and poor prognoses." (PMID 38971772, 2024). "For instance, circHECTD1 contributes to glioma progression by regulating the miR-296-3p/SLC10A7 axis, and circ-TOP2A regulates glioma progression via miR-346/SUSD2." (PMID 37575469, 2023). "Top2a substantially increases the metastatic behaviors of glioma cells in a β-catenin-dependent way." (PMID 36678591, 2023). "Top2a physically interacts with β-catenin and enhances β-catenin’s entrance into glioma cell nuclei." (PMID 36678591, 2023). "Studies using data from the Oncomine database have shown that TOP2A is significantly overexpressed in glioma tissue compared to normal controls." (PMID 37593751, 2023). "Compared with non-tumor tissues, FAM204A was down-regulated, but TNPO1 and TOP2A were up-regulated in glioma tissues." (PMID 35093128, 2022). "Mechanistically, TOP2A effectively induced glioma cell growth and invasion in a β-catenin-dependent manner." (PMID 35012441, 2022). "In our study, GEO datasets in combination with TCGA data suggested that TOP2A expression was profoundly elevated in glioma." (PMID 35012441, 2022). "Overall, we pinpoint TOP2A as a critical activator of the Wnt/β-catenin pathway in glioma, promoting cell growth, migration, and invasion." (PMID 35012441, 2022). "TOP2A depletion attenuated the metastatic potential of glioma cells via promoting the translocation of β-catenin into the nucleus." (PMID 35012441, 2022). "DNA topoisomerase II alpha (TOP2A) reportedly plays a crucial role in several cancers, however, the precise regulatory role of TOP2A in metastatic characteristics of glioma is still poorly understood." (PMID 35012441, 2022). "Although TOP2A has been shown to play crucial roles in cancers, it is imperative to investigate the pro-metastasizing function of TOP2A in glioma." (PMID 35012441, 2022). "These outcomes demonstrated that the pro-metastatic ability of TOP2A in glioma cells was dependent on β-catenin, which in turn mediated the cancer-promoting role of TOP2A." (PMID 35012441, 2022). "In sum, TOP2A physically binds with β-catenin and facilitates β-catenin entry into the nucleus of glioma cells." (PMID 35012441, 2022). "A typical feature of glioma is diffuse tumor invasion, and we sought to determine the biological significance of TOP2A in glioma migration/invasion." (PMID 35012441, 2022). "This study presents the first evidence that TOP2A has an important role in promoting glioma cells, reinforcing the view that TOP2A is a critical factor in glioma development." (PMID 35012441, 2022).
glioma (continued). "Herein, after β-catenin deletion in the TOP2A-overexpressing glioma cell, the growth and aggressive traits were partly retained." (PMID 35012441, 2022). "In our study, inhibition of TOP2A reduced the proliferation, migration, and invasive capacities of glioma cells." (PMID 35012441, 2022). "Herein, we sought to elucidate the mechanisms by which TOP2A affects the metastatic phenotypes of glioma." (PMID 35012441, 2022). "While all 4 target genes predicted reduced OS and PFI in LGG patients, both FANCB and TOP2A showed a protective role in the risk score model, indicating the controversial effect of FANCB and TOP2A in glioma patients." (PMID 34868977, 2021). "Overexpression of miR-144-3p can suppress proliferation in glioma cells by targeting TOP2A and inhibit the growth of glioma xenografts in nude mice." (PMID 33046994, 2020). "TOP2A is a direct target gene for miR-144-3p, and TOP2A promotes the proliferation and migration of glioma cells." (PMID 30544723, 2018). "In this study, we found that TOP2A was highly expressed in HCMV-positive glioma compared with HCMV-negative glioma." (PMID 30544723, 2018). "qPCR analysis was performed to test the transfection efficiency in glioma cell lines and measure the TOP2A mRNA expression level." (PMID 30544723, 2018). "Taken together, these results show that miR-144-3p inhibited growth and promoted apoptosis in glioma cells by targeting TOP2A." (PMID 30544723, 2018). "Previous research has shown that its expression is significantly downregulated in osteosarcoma, lung cancer, prostate cancer and glioblastoma.However, the molecular mechanism that regulates TOP2A expression is still unclear for HCMV-positive glioma." (PMID 30544723, 2018). "Forced expression of miR-144-3p was explored to lower the expression levels of TOP2A in glioma cells, which promoted malignant progression." (PMID 30544723, 2018). "As a result, TOP2A knockdown significantly reduced cell growth and enhanced apoptosis in glioma cells infected with HCMV." (PMID 30544723, 2018). "Further, down regulation of TOP2A using RNA interference in glioma cells resulted in temozolomide chemosresistance." (PMID 23646114, 2013). "The variable positive expression of TOP2A in all 160 glioma tissues was detected by IHC." (PMID 41284119, 2025). "Recent studies have shown that TOP2A is highly expressed in glioma tissue and may be related to the tumor survival prognosis of glioma." (PMID 41284119, 2025). "Finally, we used immunohistochemistry experiments to perform quantitative and qualitative analysis of TOP2A in glioma tissue." (PMID 41284119, 2025). "The expression of TOP2A in glioma tissues was evaluated by immunohistochemistry, and the results showed that TOP2A was significantly correlated with the gliomas of varying degrees of malignancy (Because we collect fewer cases with WHO grade I, they will not be discussed in this study)." (PMID 41284119, 2025). "Correlation analysis (K-M survival curve) was performed in connection with the expression of TOP2A in glioma with clinical prognosis, and the results showed that the survival prognosis of the TOP2A high expression group was significantly worse than that of the low expression group." (PMID 41284119, 2025). "Moreover, canonical oncogenic proliferation markers MKI67 and TOP2A were upregulated in the CDC20+KIF20A+PTTG1+ cell subpopulation of glioma samples." (PMID 40047299, 2025). "Therefore, high expression of TOP2A is one of the important target genes that promote the development of high-grade glioma and is a potential target for the diagnosis and treatment of high-grade glioma." (PMID 41284119, 2025). "In addition, HCMV infection can promote TOP2A high expression after glioma infection, thereby promoting the malignant progression of glioma." (PMID 41284119, 2025).
glioma (continued). "In line with the model’s prediction of higher Etoposide sensitivity in wild-type IDH (wtIDH) gliomas compared to mutant IDH (mIDH) gliomas, transcriptomic analysis revealed significantly elevated TOP2A expression in wtIDH tumor samples relative to both mIDH gliomas and normal brain tissue." (PMID 40563807, 2025). "TOP2A downregulation was also detected in ORC6 KO intracranial glioma xenograft tissue." (PMID 38971772, 2024). "Our data strongly supported that ORC6 regulates the expression of TOP2A within glioma cells." (PMID 38971772, 2024). "Subsequent studies unveiled a significant decrease in the mRNA and protein expression levels of Cyclin A2, Cyclin B2, and TOP2A within koORC6 P1 glioma xenograft tissues, where elevated levels of cleaved-caspase-3, cleaved-caspase-9, and cleaved-PARP-1 were detected, indicating apoptosis activation." (PMID 38971772, 2024). "This overexpression suggests that TOP2A may play a critical role in the development and progression of gliomas." (PMID 37593751, 2023). "Overall survival of TOP2A expression in glioma patients was identified from the TCGA database." (PMID 35012441, 2022). "Furthermore, the mRNA level and protein expression of β-catenin were raised by TOP2A overexpression and were decreased when TOP2A was deleted in glioma cells." (PMID 35012441, 2022). "A highly conserved lncRNA, LINC00461, which functions as an essential regulator in glioma formation and regulates the expressions of genes such as DNA topoisomerase II Alpha (TOP2A), B-cell lymphoma 2 (BCL2), and integrin β3 (ITGB3), was identified to be remarkably downregulated by HDAC6 depletion." (PMID 35109908, 2022). "This study revealed that TOP2A expression is aberrantly highly expressed in glioma, and abnormally high TOP2A expression could serve as a prognostic indicator." (PMID 35012441, 2022). "TOP2A effectively intensifies glioma cell metastatic phenotypes in a β-catenin-dependent manner." (PMID 35012441, 2022). "It has been previously verified that miR-144-3p could induce glioma cell apoptosis and suppress cell migration by modulating TOP2A." (PMID 35012441, 2022). "Among TME-infiltrating male MG, we found cluster MG8 characterized by a high expression of genes encoding proliferation-related proteins (Stmn1, Tubb5, Tuba1b, Cdk1, and Top2a), which is consistent with the observed proliferation of MG within glioma TME, as previously reported." (PMID 33608526, 2021). "ECONEXIN is a potential oncogene that regulates TOP2A by sponging miR-411-5p in glioma." (PMID 32978519, 2020). "Interestingly, temozolomide inhibited TOP2A activity and siRNA knocked down of TOP2A rendered a glioma cell line resist." (PMID 30405856, 2018). "We identified TOP2A as a direct target gene of miR-144-3p for HCMV-infected glioma cells." (PMID 30544723, 2018). "In conclusion, we propose that tachyplesin I may down-regulate cathepsins in lysome and up-regulate TOP2A to inhibit migration and promote apoptosis in glioma, thus contributing to its anti-tumor activity." (PMID 28106765, 2017). "TOP2A is involved in human glioma response to irradiation and regulation of apoptosis." (PMID 29242629, 2017). "Furthermore, TOP2A depletion attenuated the metastatic potential of glioma cells." (PMID 35012441, 2022). "Finally, TOP2A was significantly upregulated in glioma cell lines compared to HEB cells." (PMID 35012441, 2022). "Additionally, TOP2A was found to be a prognostic factor for patients with glioma." (PMID 35012441, 2022). "But multivariate COX regression analysis showed that TOP2A, AGE, and GRADE are considered clinically relevant to glioma." (PMID 41284119, 2025). "miR-144-3p, a member of the miR-144/451 cluster, acts as a tumor suppressor by directly targeting TOP2A, which is overexpressed in HCMV-positive gliomas." (PMID 41471245, 2025). "CENPF, TOP2A, UBE2C, PBK, and MKI67 were strongly expressed in glioma clusters, indicating the presence of progenitor cells." (PMID 39333557, 2024).
glioma (continued). "ORC6 depletion, inhibited proliferation, decreased expression of Cyclin A2/B2/TOP2A, and increased apoptosis were detected within these ORC6 KO intracranial glioma xenografts." (PMID 38971772, 2024). "In light of bioinformatic studies highlighting the close association between ORC6 and key oncogenic genes, including Cyclin A2, Cyclin B2, and TOP2A in GBM, our study explored the potential role of ORC6 in regulating their expression in glioma cells." (PMID 38971772, 2024). "In glioma cells and tissues, GINS1 promoted cell proliferation and migration through ubiquitin-specific protease 15-mediated deubiquitination of TOP2A protein, and its high expression predicted an advanced clinical grade and a poor survival." (PMID 37627167, 2023). "KLC1 and TOP2A showed high levels of expression in almost every tumor type examined, while UCHL1 was found mainly in glioma." (PMID 36010968, 2022). "The qRT-PCR results showed that the mRNA expression levels of FAM204A and SMU1 in human glioma cell lines overall showed a downward trend compared with the HA1800, while the mRNA expression levels of TNPO1 and TOP2A showed an overall upward trend." (PMID 35093128, 2022). "ECONEXIN lncRNA is upregulated in glioma tissue and promotes cell proliferation by sponging miR-411–5p and altering TOP2A (DNA topoisomerase II alpha) gene expression." (PMID 34316694, 2021). "Some intriguing aspects of the core gene set identified in this study include the well-studied glioma-related genes ANGPT2, CD44, SPP1, STAT3, PDGRFA, and TOP2A (all up-regulated), and BRSK1, DKK3, FGFR2, MAPK9, MEF2C, and PTEN (all down-regulated)." (PMID 29352201, 2018). "To explore the molecular mechanism of TOP2A in HCMV-positive glioma, we measured the transcriptional and protein expression of TOP2A in two glioma cell lines, U87 and U251, by comparing the results before and after infection with the AD169 HCMV strain." (PMID 30544723, 2018). "We discovered that the overexpression of miR-144-3p downregulated the overexpression of TOP2A and inhibited the proliferation, clone formation, and invasion of HCMV-positive glioma in vitro." (PMID 30544723, 2018). "In glioma, high levels of TOP2A mRNA have been noted in GBM in comparison with grade II and III astrocytomas and also correlate with tumor TOP2A protein levels." (PMID 30405856, 2018). "High TOP2A expression in GBM was correlated with cell proliferation and malignant transformation in HCMV-positive glioma cells." (PMID 30544723, 2018). "Restoration of miR-144-3p expression inhibits glioma growth in xenograft models, indicating that the upregulation of miR-144-3p can suppress the proliferation of HCMV-positive GB cells through inhibition of the TOP2A pathway." (PMID 41471245, 2025). "In contrast, in P1 glioma cells overexpressing ORC6, “oeORC6-Slc1” and “oeORC6-Slc2,” there was a significant elevation observed in both mRNA and protein expression levels of Cyclin A2, Cyclin B2, and TOP2A." (PMID 38971772, 2024). "Similarly, glioma tissues, including glioblastoma (GBM) and low-grade glioma (LGG), exhibited higher expressions of TOP2A." (PMID 35012441, 2022). "Moreover, we found both high TOP2A mRNA expression and protein expression in HCMV-infected glioma cells." (PMID 30544723, 2018). "Furthermore, we measured the expression of TOP2A and miR-144-3p during HCMV infection of glioma cell lines with miR-144-3p, anti-miR-144-3p and untreated." (PMID 30544723, 2018). "In addition, Deguchi and Song found that TOP2A is involved in the proliferation of glioma through lncRNA ECONEXIN and miR-144-3p, but the relationship between TOP2A and proliferation, migration and invasion of MB remains unclear." (PMID 35912241, 2022). "However, the pathological role of TOP2A is not well defined for glioma." (PMID 35012441, 2022).
hepatocellular carcinoma (41 papers, 2015 to 2026). A malignant tumor that arises from hepatocytes. "Survival analysis indicated that the expression levels of CCNA2, CHK1, E2F1, and TOP2A are significantly associated with the survival prognosis of hepatocellular carcinoma patients, with p-values of 0.0038, 0.00013, 0.013, and 0.00066, respectively." (PMID 40573296, 2025). "TOP2A is highly expressed in many tumor types, such as non-small cell lung cancer, hepatocellular carcinoma, and has proven to be a reliable profile marker, associated with disease progression and poor prognosis." (PMID 39846632, 2024). "TOP2A was significantly upregulated in dedifferentiated hepatocellular carcinoma and hepatocellular carcinoma with loss of chromosome 13q." (PMID 35342754, 2022). "Top2a was overexpressed in hepatocellular carcinoma and associated with early age onset, shorter patient survival, and chemoresistance." (PMID 31828136, 2019). "In hepatocellular carcinoma, TOP2a overexpression is associated with chemoresistance." (PMID 28556593, 2017). "Our results suggest that TOP2A is overexpressed in patients with hepatocellular carcinoma (HCC) and that its mRNA expression is significantly associated with individual cancer stage in HCC patients." (PMID 35033076, 2022). "TOP2A has also been reported to involve in resistance to regorafenib, a common treatment for hepatocellular carcinoma (HCC)." (PMID 40831931, 2025). "In line with our findings, other studies have also reported that elevated TOP2A expression correlates with poor prognosis in several cancers, including hepatocellular carcinoma." (PMID 40099956, 2025). "GO and GP results show the significance of TOP2A, which is involved in growth of hepatocellular carcinomas." (PMID 38549123, 2024). "Of note, LINC00265/miR-101-3p/TOP2A have been found to regulate the immune checkpoints expression and modulate the immune status by positively correlated with macrophages in hepatocellular carcinoma." (PMID 37620751, 2023). "The aim of this study is to detect if there is an association between expression of some long non coding RNAS (LNCRNAs) as (RAMS11, LINC01564), CBX4, and TOP2A and clinical; pathological characteristic of hepatocellular carcinoma in Egyptian patients." (PMID 36672564, 2022). "On the other hand, TOP2A promotes the metastasis of hepatocellular carcinoma by regulating the EMT process." (PMID 35069905, 2022). "The study in this paper shows that the expression of the TOP2A gene is raised in the human hepatocellular carcinoma family, and its high expression is related to poor prognosis in liver cancer patients." (PMID 35033076, 2022). "Together, we propose that TOP2A is negatively regulated by miR-144-3p and affects the progression of hepatocellular carcinoma." (PMID 35069905, 2022). "The results showed that TOP2A was differentially expressed in a variety of tumors, and the expression of TOP2A was higher in hepatocellular carcinoma tissues than in adjacent tissues (p < 0.001)." (PMID 35033076, 2022). "RT-qPCR and Western blot were used to detect both the mRNA and protein expression of TOP2A in six human hepatoma and normal LO2 cell lines (MHCC97-H, Huh-7, LM3, HepG2, SMMC-7402, Hep-3B and LO2)." (PMID 35069905, 2022). "AURKA, CDK1, CCNB1 and TOP2A were significantly upregulated and correlated with poor prognosis in hepatocellular carcinoma, AUC values of which were 95.7, 96.9, 98.1 and 96.1% respectively." (PMID 35078445, 2022). "Taken together, our study supports TOP2A as a potential new biomarker for the prevention, diagnosis, and treatment of hepatocellular carcinoma." (PMID 35033076, 2022). "As an extensive differentially expressed gene in 13 cancer types, a high level of TOP2A expression has been indicated in multiple cancers, including high-grade serous ovarian cancer, hepatocellular carcinoma, esophageal squamous cell carcinoma." (PMID 36288358, 2022).